OGN (osteoglycin)
Diseases named in the same sentence as OGN in open-access papers (continued):
Sharing a sentence is not in itself a finding about the gene and the disease.
meningioma (continued). "OGN-overexpressing meningioma cells demonstrated an elevated rate of cell proliferation, cell cycle activation, and colony formation as compared with cells transfected with control vector." (PMID 28923059, 2017). "Meningioma cells with knockdown of OGN also demonstrated significantly reduced cell proliferation and expression of the cell cycle markers cyclin A2 and cyclin B1, compared to cells with stable expression of OGN." (PMID 28923059, 2017). "Lastly, introduction of an AKT inhibitor reduced OGN expression in meningioma cells and resulted in increased cell death and autophagy, suggestive of a reciprocal relationship between OGN and AKT." (PMID 28923059, 2017). "The impact of OGN on cell proliferation, colony formation, and mitogenic signaling cascades was assessed in a human meningioma cell line (IOMM-Lee) with stable overexpression of OGN." (PMID 28923059, 2017). "This study lays a foundation for the incorporation of OGN expression into personalized treatment for meningiomas." (PMID 28923059, 2017). "Consistent with the RNA level, OGN protein expression was higher in meningothelial and atypical subtypes, but lower in psammomatous and rhabdoid meningiomas as determined by Western blotting." (PMID 28923059, 2017). "AKT inhibition reduces OGN protein levels in meningioma cells, with a concomitant increase in cell death, which provides a promising treatment option for meningiomas with OGN overexpression." (PMID 28923059, 2017). "Therefore, further studies should examine how chrysophanol affects the expression of OGN in malignant meningioma cells." (PMID 33622177, 2021). "OGN mRNA expression in human meningiomas was assessed by RNA microarray and RNAscope." (PMID 28923059, 2017). "Furthermore, stable expression of OGN in meningioma cells produced a significant increase in phospho-AKT." (PMID 28923059, 2017). "We identify OGN as a novel oncogene in meningioma proliferation." (PMID 28923059, 2017). "We further analyzed 35 meningiomas with the whole exome or whole genome sequencing data, the frequency analysis of genetic alteration reveals increased NF2 or chr22 loss in human meningiomas with higher OGN mRNA expression." (PMID 28923059, 2017). "The sensitivity of OGN-expressing meningioma cells to AKT inhibition suggests that OGN expression may serve as an addition biomarker to stratify the response of aggressive meningiomas to AKT inhibitors." (PMID 28923059, 2017). "Interestingly, we identified synergy between OGN and previously identified oncogenic signaling pathways in meningioma." (PMID 28923059, 2017). "In addition, meningiomas with high OGN mRNA levels harbor more frequent NF2 or chr22 loss than those with low OGN mRNA levels, and OGN protein expression was higher in meningiomas with NF2 loss." (PMID 28923059, 2017). "For example, it has been reported that chrysophanol inhibits the osteoglycin/mTOR and activates NF2 signaling pathways to reduce viability and proliferation of malignant meningioma cells." (PMID 34519612, 2021). "Meningioma cell line HBL-52 were incubated with varying doses of chrysophanol (0–90 μM) for different time points, and osteoglycin (OGN) was overexpressed or inhibited in some cell cultures to assess its roles." (PMID 33622177, 2021). "To explore the possible therapeutic avenues in the setting of OGN overexpression in meningioma and its activation of mTOR and AKT, we tested the effect of a small molecule inhibitor of AKT (AKTVIII) on meningioma cells." (PMID 28923059, 2017). "We observed no mutation or copy number alterations in OGN in an extensive series of meningioma samples and cell lines that underwent next-generation sequencing, which suggests that wildtype OGN may function as a co-activator of signals that promote meningioma growth and neoplasia formation." (PMID 28923059, 2017). "OGN appears to downregulate NF2, the canonical tumor suppressor altered in approximately half of meningiomas." (PMID 28923059, 2017).
meningioma (continued). "However, whether OGN is involved in meningioma development is currently unknown." (PMID 28923059, 2017). "As compared to negative control, OGN mRNA expression was dramatically increased in meningiomas (68 samples) compared to 8 other CNS tumors and normal brain tissue (p < 0.0001)." (PMID 28923059, 2017). "We could not clearly demonstrate the interact of chrysophanol with OGN protein in malignant meningioma cells." (PMID 33622177, 2021). "We found that OGN overexpression increased cell proliferation, that knockdown reduced cell growth, and that cells expressing high levels of OGN were sensitive to AKT inhibition; thereby, establishing for the first time, a potential mitogenic effect for OGN in meningioma." (PMID 28923059, 2017). "Thus, investigating the expression and activation of OGN, mTOR, and NF2 signaling in meningioma cells will not only uncover key molecular mechanisms, but may also provide promising targets for the treatment of meningioma." (PMID 33622177, 2021). "We observed robust OGN expression across a wide range of meningioma histological subtypes and grades, at significantly higher levels than eight other CNS tumors and normal brain, posing OGN as an appealing target for those meningiomas which currently do not have pharmacologic treatment options." (PMID 28923059, 2017). "OGN is known to interact with p-mTOR and NF2 during meningioma development, but how OGN affects these other proteins is not clear." (PMID 33622177, 2021).
myocardial infarction (7 papers, 2017 to 2025). Gross necrosis of the myocardium, as a result of interruption of the blood supply to the area, as in coronary thrombosis. "Contrarily, a 34-kDa OGN variant was highly abundant in murine myocardial infarcts, temporally and spatially associated with collagen fibrillogenesis." (PMID 27878326, 2017). "Compared with LTBP2 and OGN, PTN exhibited enrichment in myocardial infarction, which is the primary cause of cardiac ischemia and subsequent heart failure." (PMID 39722892, 2024). "Upregulation of OGN, osteoglycin, has been reported to play a role in collagen maturation and deposition in mouse myocardial infarction tissue." (PMID 32423033, 2020). "This is supported by immunohistochemical staining for OGN in human myocardial infarcts, revealing that OGN staining clearly matched cardiac fibrosis." (PMID 27878326, 2017). "OGN is critical during the wound healing process after myocardial infarction by stimulating the formation of well-aligned collagen fibers in the infarct scar." (PMID 27878326, 2017). "It was also proposed that OGN might be involved in the regulation of cardiac dysfunction and adverse remodeling after myocardial infarction in HF." (PMID 38397416, 2024). "Notably, an upsurge in OGN expression within infarct scars contributes to the proper maturation of collagen, thereby preventing cardiac rupture and counteracting adverse remodeling post-myocardial infarction (MI)." (PMID 39717447, 2024). "Increased circulating OGN has also been observed in ischemic HF patients experiencing myocardial infarction compared to patients with non-ischemic HF and thus it has been proposed as a biomarker for ischemic HF with pre-existing myocardial infarction." (PMID 32423033, 2020). "More specifically, compared with those with nonischemic heart failure, circulating OGN levels were significantly increased in patients with a previous history of myocardial infarction (MI) and correlated with survival, left ventricular volumes, and fibrosis." (PMID 36421687, 2022).
ovarian carcinoma (7 papers, 2021 to 2025). A malignant neoplasm originating from the surface ovarian epithelium. "OGN overexpression in CAFs significantly inhibited ovarian cancer cell viability, DNA synthesis, and cell invasion." (PMID 38402185, 2024). "According to GSE35250, OGN was significantly downregulated in normal fibroblasts co-cultured with ovarian cancer cells." (PMID 38402185, 2024). "Considering the downregulation of OGN in several cancers and its anti-tumor function, online datasets were analyzed to confirm OGN expression in ovarian cancer." (PMID 38402185, 2024). "OGN expression within CAFs and NFs and the effects of conditioned culture medium derived from CAFs (CAFs or OGN-overexpressed CAFs) or NFs on ovarian cancer cells were examined." (PMID 38402185, 2024). "Herein, conditioned culture medium derived from OGN-overexpressed CAFs significantly inhibited ovarian cancer cell viability, DNA synthesis, and cell invasion." (PMID 38402185, 2024). "According to GSE40595, OGN was significantly downregulated within ovarian cancer stromal cells compared to the normal control." (PMID 38402185, 2024). "GSE40595 and GSE38666 showed differentially expressed genes between normal and ovarian cancer stroma samples; the differentially expressed genes overlapped in 37 upregulated and 2 downregulated genes, including OGN." (PMID 38402185, 2024). "Increased expression of OGN has been observed in ovarian carcinoma and has been found to exhibit a correlation with EMT signature and poor prognosis." (PMID 37605453, 2023). "OGN expression was found to be an adverse prognostic factor for both overall and progression-free survival in ovarian carcinoma patients in a Kaplan-Meier analysis." (PMID 36421687, 2022). "However, elevated expression of OGN is associated with the EMT process and shorter overall survival in ovarian carcinoma tissues." (PMID 40051609, 2025). "Taken together, miR-1290 might be the reason for OGN downregulation in CAFs, and affect the crosstalk between CAFs and cancer cells, thereby modulating the malignant behaviors of ovarian cancer cells." (PMID 38402185, 2024). "Although several datasets from Gene Expression Omnibus (GEO), such as GSE40595, GSE35250, and GSE14407, indicate the downregulation of OGN in ovarian cancer, the specific effect of OGN on ovarian cancer remains unclear." (PMID 38402185, 2024). "Altogether, a miR-1290/OGN axis in CAFs in ovarian cancer, which might affect ovarian cancer cell phenotypes was demonstrated." (PMID 38402185, 2024). "Then, when ovarian cancer cells were cultured in a conditioned medium derived from CAFs co-transduced with miR-1290 mimics and OGN-OE, the effects of miR-1290 overexpression were partially reversed by OGN overexpression." (PMID 38402185, 2024). "Finally, the effects of conditioned culture medium derived from CAFs co-transduced with OGN-OE and miR-1290 mimics on ovarian cancer cells were examined." (PMID 38402185, 2024). "However, in pituitary tumors and ovarian carcinoma, OGN expression is differentially dependent on the tumor type." (PMID 36421687, 2022). "Finally, when ovarian cancer cells in a conditioned medium derived from CAFs co-transduced with miR-1290 mimics and OGN-OE were cultured, the effects of miR-1290 overexpression were partially reversed by OGN overexpression." (PMID 38402185, 2024). "Thus, OGN overexpression in CAFs could inhibit the malignant behaviors of ovarian cancer cells, possibly by affecting cancer cell proliferation and adhesion." (PMID 38402185, 2024). "OGN overexpression also changed epithelial-mesenchymal transition (EMT) markers and promoted mTOR and Akt phosphorylation in ovarian cancer cells." (PMID 38402185, 2024). "Further analysis showed that ovarian cancer patients with high level of CITED2, LYVE1, OGN, RAP1A, and TBC1D22A had a poor prognosis that that with level of CITED2, LYVE1, OGN, RAP1A, and TBC1D22A (all p < 0.05)." (PMID 37784081, 2023).
ovarian carcinoma (continued). "The protein level of CITED2, LYVE1, OGN, RAP1A, and TBC1D22A were higher in ovarian cancer tissues than that in normal tissues." (PMID 37784081, 2023). "Hence, we speculate that CAFs may secrete extracellular vesicles or exosomes containing miR-1290 and OGN, thereby affecting the expression of E-cadherin, mTOR and AKT in ovarian cancer cells and mediating the proliferation and metastasis of ovarian cancer cells." (PMID 38402185, 2024).
heart failure (6 papers, 2022 to 2025). Inability of the heart to pump blood at an adequate rate to meet tissue metabolic requirements. "Utilizing machine learning and network-based approach, OGN was identified as a biomarker covering multiple pathogenic pathways for diagnosing heart failure." (PMID 40060963, 2025). "By intersecting the findings from all three algorithms, we pinpointed four diagnostic genes for the pre-decompensation stage of heart failure: SMOC2, OGN, FCN3, and SERPINA3." (PMID 39717447, 2024). "FOS and ALOX5 were mainly expressed in macrophages and OGN was mainly expressed in fibroblasts, which were all significantly expressed in disease progression and required more attention to explore the effects on heart failure." (PMID 40060963, 2025). "The screened hub genes, including OGN, FOS and ALOX5, were validated using single-cell sequencing data, cell lines and human samples, which can be therapeutic targets for the treatment to cell senescence under hypoxia and prediction to heart failure progression to HFpEF." (PMID 40060963, 2025).
laryngeal carcinoma (6 papers, 2014 to 2025). Carcinoma that arises from the laryngeal epithelium. "Furthermore, we first time show that PFN1, NCL, CNDP2 and OGN may be potential diagnostic and therapeutic targets for laryngeal carcinoma, and demonstrate that PFN1 is involved in the migration of human squamous cells." (PMID 24587265, 2014). "A study investigated proteomics for diagnostic biomarkers of laryngeal cancer, and four differential proteins (PFN1, NCL, CNDP2, and OGN) with expressional changes were selected to test for differential expressions." (PMID 40051609, 2025). "Next, semiquantitative RT-PCR was performed to detect the mRNA levels of PFN1, NCL, CNDP2 and OGN in 8 cases of paired laryngeal carcinoma tissues." (PMID 24587265, 2014). "And the results revealed that the expression of PFN1, NCL, and CNDP2 was elevated and that of OGN was reduced in laryngeal carcinoma tissue compared with the adjacent normal tissue." (PMID 24587265, 2014). "Here, our validation experiments demonstrated the significant down-expression of OGN in a large group of laryngeal carcinoma patients, hinting that OGN may be a potential tumour suppressor gene involved in laryngeal carcinoma initiation and progression." (PMID 24587265, 2014). "Thus, the expression of PFN1, NCL, CNDP2 and OGN were further investigated employing a large collection of human laryngeal carcinoma tissues." (PMID 24587265, 2014). "Altogether, our present data first time show that PFN1, NCL, CNDP2 and OGN are novel potential biomarkers for diagnosis and therapeutic targets for laryngeal carcinoma, and PFN1 is involved in the metastasis of laryngeal carcinoma." (PMID 24587265, 2014). "Taken together, in this study, the use of 2D LC-MS/MS identified 281 significantly differentially expressed proteins in human laryngeal carcinoma, and four differential proteins (PFN1, NCL, CNDP2 and OGN) with expressional changes were selectively verified." (PMID 24587265, 2014).
coronary artery disease (5 papers, 2019 to 2023). "In this line, a couple of studies found an association between high serum OGN levels and poor coronary collateralization in patients with coronary artery disease, as well as increased arterial stiffness in hypertensive patients." (PMID 34065223, 2021). "A study showed that OGN expression was increased in patients with coronary heart disease compared with normal subjects and was related to the severity of the coronary lesions." (PMID 36863704, 2023). "Within this line, it has been suggested that osteoglycin could be used as a prognostic biomarker in patients with coronary artery disease." (PMID 37819194, 2023). "Some studies have reported a close relationship between osteoglycin levels and the risk of suffering CVD showing an association between an increase of osteoglycin in serum and patients with coronary artery disease, as well as, increased arterial stiffness in hypertensive patients." (PMID 37819194, 2023). "In a study examining the prognostic value of certain biomarker proteins for coronary artery disease patients, circulating osteoglycin, whose expression was elevated in vulnerable atherosclerotic plaques, was suggested as a promising biomarker of adverse cardiovascular events." (PMID 31703357, 2019). "It has been shown that the amount of osteoglycin in the blood of patients with coronary heart disease increases, but does not correlate with the severity of the disease." (PMID 34948066, 2021).
diabetes (5 papers, 2018 to 2025). "Another study reported that osteoglycin levels are higher in individuals with diabetes mellitus compared to controls; however, this might also reflect differences in BMI and renal function, as these traits have been associated with osteoglycin levels." (PMID 38549032, 2024). "In postmenopausal women with T2D, osteoglycin levels are associated with duration of diabetes, decreased aBMD and presence of vertebral fractures but not N-terminal cross-linked telopeptide of type-I collagen (NTX), osteocalcin (OC), fasting glucose or HbA1c." (PMID 33790870, 2021). "Although mice with osteoglycin knockout display altered metabolic and bone profile suggesting a bone-muscle- and pancreas-axis, we could not find any association between osteoglycin and these markers in humans with diabetes." (PMID 33790870, 2021). "Individuals with type 2 diabetes have higher levels of osteoglycin compared to those without diabetes." (PMID 38549032, 2024). "Two different models were assessed, including the main impaired kidney function risk factors (age, hypertension, dyslipidemia, HbA1c level, tobacco use, and years of diabetes duration) with and without the serum OGN level." (PMID 34065223, 2021). "OGN, Osteoglycin (mimecan) is a class II SLRP with diverse roles in ECM assembly, regulates bone formation along with TGF‐β1/TGF‐β2 to control collagen fibrillogenesis and also has regulatory roles in metabolic health, cancer and diabetes regulating glucose homeostasis." (PMID 41376803, 2025). "There is a consensus on the fact that osteoglycin is expressed and secreted from muscle cells and future studies could focus on S-osteoglycin levels in human subjects with or without diabetes mellitus as well as before and after exercise." (PMID 33790870, 2021).
bladder cancer (4 papers, 2020 to 2025). "It has been observed in bladder cancer that ECRG4 promotes OGN expression by upregulating NFIC, preventing the activation of NF-KB downstream pathways, thus inhibiting cell proliferation and migration." (PMID 35197484, 2022). "For instance, NFIC can promote osteoglycin expression by binding to its promoter region to repress bladder cancer by limiting cell proliferation and invasiveness." (PMID 34930914, 2021). "Both ECRG4 and OGN function as tumor suppressors in the bladder, with ECRG4 overexpression inhibiting NF-kB signaling and promoting NFIC/OGN signaling in bladder cancer cells." (PMID 40051609, 2025).